C2CD4D (C2 calcium dependent domain containing 4D)
Synonyms: FAM148D
Tractability: No criterion of Open Targets' tractability assessment is met for any kind of drug.
Gene: Protein-coding gene on chromosome 1 (151,837,818 to 151,840,557, reverse strand). Ensembl gene ENSG00000225556.
Genetic constraint (gnomAD): Loss-of-function variants: 1 observed, 0.44 expected, observed/expected ratio (o/e) 2.29. That is too few expected variants to judge how well the gene tolerates losing a copy. Missense variants: 552 observed, 430.86 expected, observed/expected ratio (o/e) 1.28, 90% interval 1.19 to 1.38. Synonymous variants: 269 observed, 203.81 expected, observed/expected ratio (o/e) 1.32, 90% interval 1.19 to 1.46.
Homologues: Orthologues: chimpanzee C2CD4D (99% identical), macaque C2CD4D (97% identical), pig C2CD4D (86% identical), rat C2cd4d (80% identical), mouse C2cd4d (79% identical), guinea pig C2CD4D (74% identical). Paralogues in human: C2CD4C (37% identical), C2CD4B (30% identical), C2CD4A (29% identical), SYT10 (16% identical), SYT11 (16% identical), SYT6 (16% identical), SYT9 (16% identical), SYT3 (15% identical), SYT4 (15% identical), RPH3A (15% identical), SYTL1 (15% identical), SYTL2 (15% identical), and 19 more.